ARHGAP17 (Rho GTPase activating protein 17)
Description:
Rho GTPase-activating protein involved in the maintenance of tight junction by regulating the activity of CDC42, thereby playing a central role in apical polarity of epithelial cells. Specifically acts as a GTPase activator for the CDC42 GTPase by converting it to an inactive GDP-bound state. The complex formed with AMOT acts by regulating the uptake of polarity proteins at tight junctions, possibly by deciding whether tight junction transmembrane proteins are recycled back to the plasma membrane or sent elsewhere. Participates in the Ca(2+)-dependent regulation of exocytosis, possibly by catalyzing GTPase activity of Rho family proteins and by inducing the reorganization of the cortical actin filaments. Acts as a GTPase activator in vitro for RAC1.
Synonyms: RICH-1; RICH1; MSTP066; MSTP110; FLJ10308; NADRIN; FLJ13219; WBP15; MST066; MST110; MSTP038; PP367; PP4534
Tractability: Antibody: its Gene Ontology location is reachable by antibodies, with high confidence; UniProt places it where antibodies can reach, with medium confidence; the Human Protein Atlas places it where antibodies can reach. PROTAC: ubiquitination databases record sites on it; its protein half-life has been measured.
Gene: Protein-coding gene on chromosome 16 (24,919,389 to 25,015,666, reverse strand). Ensembl gene ENSG00000140750.
Subcellular location: Membrane; Cytoplasm; Cell junction, tight junction
Subcellular location (Human Protein Atlas): Cytosol; Plasma membrane
Pathways (Reactome):
Signal Transduction: CDC42 GTPase cycle; RAC1 GTPase cycle; RAC2 GTPase cycle; RAC3 GTPase cycle; RHOD GTPase cycle; RHOQ GTPase cycle
Gene Ontology:
Molecular function: protein binding; GTPase activator activity
Biological process: negative regulation of small GTPase mediated signal transduction; regulation of actin cytoskeleton organization; regulation of Rac protein signal transduction; signal transduction
Cellular component: plasma membrane; bicellular tight junction; cytoplasm; membrane
Genetic constraint (gnomAD): Loss-of-function variants: 50 observed, 84.07 expected, observed/expected ratio (o/e) 0.59, 90% interval 0.47 to 0.75. The upper end of that interval is the gene's LOEUF score, 0.75, which puts it in group 3 of 6, group 1 being the genes least tolerant of losing a copy. Missense variants: 967 observed, 1,045.7 expected, observed/expected ratio (o/e) 0.92, 90% interval 0.88 to 0.98. Synonymous variants: 394 observed, 400.87 expected, observed/expected ratio (o/e) 0.98, 90% interval 0.9 to 1.07.
Homologues: Orthologues: chimpanzee ARHGAP17 (99% identical), macaque ARHGAP17 (94% identical), pig ARHGAP17 (91% identical), guinea pig ARHGAP17 (91% identical), rabbit ARHGAP17 (88% identical), dog ARHGAP17 (87% identical), rat Arhgap17 (84% identical), mouse Arhgap17 (73% identical), tropical clawed frog arhgap17 (57% identical), zebrafish arhgap17a (56% identical), zebrafish arhgap17b (39% identical), Drosophila melanogaster RhoGAP92B (25% identical), and 2 more. Paralogues in human: ARHGAP44 (44% identical), SH3BP1 (34% identical).
Diseases named in the same sentence as ARHGAP17 in open-access papers:
ARHGAP17 is named in the same sentence as 19 diseases in open-access papers, as found by Europe PMC text mining. Sharing a sentence is not in itself a finding about the gene and the disease. The quoted sentences say what the papers report.
colitis (5 papers, 2016 to 2025). Inflammation of the colon. "Considering the deleterious effects of DSS on IECs directly, there is a possibility that an increased severity of DSS-induced colitis in Arhgap17-deficient mice is due to the differential accumulation of DSS in IECs." (PMID 27229483, 2016). "Interestingly, Arhgap17-deficient mice showed increased sensitivity to DSS-induced colitis similar to Tff3 knockout mice." (PMID 27229483, 2016). "However, the Arhgap17-deficient mice exhibited increased susceptibility to DSS-induced colitis likely associated with a rapid accumulation of DSS in the intraluminal cells and with increased vulnerability of the inner mucus layer." (PMID 27229483, 2016). "Arhgap17-deficient mice are known for enhanced permeability and aberrant tight junction in the gut without colitis." (PMID 37371794, 2023). "Arhgap17-deficiency, however, was not enough to develop spontaneous colitis and disturb intestinal homeostasis, indicating the maintenance of epithelial barrier function in the absence of Arhgap17." (PMID 27229483, 2016). "Interestingly, another recent study demonstrates that lack of Arhgap17, a RhoGTPase activating protein, causes increased epithelial permeability, not leading to spontaneous colitis but increasing the severity of DSS-induced colitis in mice." (PMID 29051760, 2017). "We found that the loss of Arhgap17 expression in the intestinal tract results in the partial mislocalization of AJC proteins with a slight increase in paracellular permeability but does not lead to spontaneous colitis." (PMID 27229483, 2016). "Arhgap17-deficient mice show an increased paracellular permeability and aberrant localization of the apical junction complex in the luminal epithelium, but do not develop spontaneous colitis." (PMID 27229483, 2016). "However, the similar FITC-DSS accumulation and apoptotic index in IECs irrespective of the genotype indicates that the damage of IECs is not likely the initial event in DSS-induced colitis in Arhgap17-deficient mice." (PMID 27229483, 2016). "That no significant increase in epithelial permeability was seen after DSS treatment in Arhgap17-deficient mice despite a dramatic TNF induction indicates that TNF-mediated disruption of intestinal TJ barriers is not an initial event of the DSS-induced colitis in these mice." (PMID 27229483, 2016). "As suggested by the in vitro study, Arhgap17 may regulate transcellular transport of macromolecules in the IECs, and regional difference of transcellular transport of DSS is likely one of the factors for region-specific effect of DSS on colitis." (PMID 27229483, 2016).
breast carcinoma (3 papers, 2022 to 2025). "Recently, ARHGAP17, a Cdc42-specific GAP, was identified as a negative regulator of invadopodia in breast cancer cells by shRNA screening for Rho GAPs." (PMID 37482421, 2023).
Bladder Cancer (2 papers, 2021 to 2023). "ARHGAP5, ARHGAP17 and ARHGAP24 promoted bladder cancer progression by establishing a tumor-promoting microenvironment or cellular mechanical property-mediated cell motility." (PMID 37175461, 2023).
colon cancer (2 papers, 2021 to 2025). "ARHGAP17 plays tumor suppressive role in colon cancer via Wnt/β-Catenin Signaling." (PMID 34131588, 2021).
COVID-19 (2 papers, 2020 to 2021). A disease caused by infection with severe acute respiratory syndrome coronavirus 2. "The 1.7-fold induced highly abundant Rho GTPase-activating protein 17 (ARHGAP17) could be involved in the repair of tight junctions, which are often damaged in COVID-19 patients." (PMID 34777295, 2021).
cervical cancer (1 paper, 2020). A primary or metastatic malignant neoplasm involving the cervix. "For example, high expression of homologs of RGA-8, including SH3BP1 (also named Nadrin and ARHGAP17) is associated with more invasive and chemo-resistant cervical cancer, and liver cancer." (PMID 33243762, 2020).
colon disorders (1 paper, 2023). "Mechanically, the Wnt signaling pathway contributed to the functions of ARHGAP17 in colon disorders." (PMID 37371794, 2023).
colorectal cancer (1 paper, 2024). A primary or metastatic malignant neoplasm that affects the colon or rectum. "Evidence suggests that overexpression of ARHGAP17 exerts anticancer effect on colorectal cancer by inhibiting Wnt/β-catenin signaling pathway." (PMID 38243347, 2024).
lung carcinoma (1 paper, 2025). "Evidence suggested that the overexpression of Rho GTPase Activating Protein 17 (ARHGAP17) inhibit the growth and invasion of CRC cells (including HCT-8 and HCT116) and attenuated lung cancer metastasis by suppressing Wnt/β-catenin signaling." (PMID 40308773, 2025).
seminoma (1 paper, 2022). A radiosensitive malignant germ cell tumor found in the testis (especially undescended), and extragonadal sites (anterior mediastinum and pineal gland). "The PSI value of ARHGAP17 was significantly upregulated in seminoma and confirmed by PCR in TCam2 cells." (PMID 36713456, 2022).
triple-negative breast carcinoma (1 paper, 2024). An invasive breast carcinoma which is negative for expression of estrogen receptor (ER), progesterone receptor (PR), and human epidermal growth factor receptor 2 (HER2). "In contrast, in the triple-negative breast cancer cell lines HCC1396, miR-4787-3p mainly acted through the regulation of ARHGAP17." (PMID 39003349, 2024).
tumor (9 papers, 2016 to 2025). "In recent times, the role of Rho GTPase Activating Protein17 (ARHGAP17) as a tumor suppressor and negative regulator for Cdc42 and Rac1 has been the subject of investigation by researchers." (PMID 40969409, 2025). "In conclusion, our results indicated that through crosstalk of tumor and leukocyte in BCa, ARHGAP17 and ARHGAP24 correlate with a tumor-promoting microenvironment through regulating CD8 + T cells and Treg infiltration and T cell function." (PMID 34307347, 2021). "pratense 400 mg/kg, suggesting that ARHGAP17 may serve as a potential tumor suppressor against TNBC xenografts." (PMID 40969409, 2025). "Moreover, Arhgap17 mediates the function of merlin tumor suppressor by downregulating Rac1 activity after being released from the angiomotin-Arhgap17 complex in the TJ21." (PMID 27229483, 2016). "Of these targets, we select ARHGAP17, FOXO3A, and PDCD4 as known tumour suppressors in cancer and experimentally validate the interaction of miR-4787-3p with their 3’UTRs." (PMID 39003349, 2024). "Rho GTPase Activating Protein 17 (ARHGAP17), a member of the GTP-active Protein family, inhibits tumor progression by down-regulating the PI3K/Akt pathway." (PMID 36713456, 2022). "T24 cells transfected with scramble shRNA (sh-NC) and shRNA targeting ARHGAP5, ARHGAP17, and ARHGAP24 were injected into nude mice subcutaneously, and knockdown of these genes significantly reduced BC tumor growth." (PMID 34307347, 2021). "Lower Th1/Th2 cell ratio, higher DC cell infiltration, and higher Treg cell infiltration were observed in ARHGAP17, ARHGAP24, and ARHGAP37 (STARD13), indicating a tumor-promoting microenvironment." (PMID 34307347, 2021).
infection (2 papers, 2021 to 2024). The state of being infected such as from the introduction of a foreign agent such as serum, vaccine, antigenic substance or organism. "However, pathogens infection significantly compromised the expression of mucin 2, ARHGAP17, RAB8A and MPP5." (PMID 38605016, 2024).
ARHGAP17 also shares sentences with these, for which no sentence is quoted: cancer (2 papers); Anxiety (1); breast tumors (1); Colon (1); lymph node metastasis (1); schwannoma (1).